PAX8 (paired box 8)
Diseases named in the same sentence as PAX8 in open-access papers (continued):
Sharing a sentence is not in itself a finding about the gene and the disease.
thyroid tumor (29 papers, 2004 to 2026). A benign or malignant neoplasm affecting the thyroid gland. "TCGA database further revealed that PAX8 is negatively co-related in BRAF mutated thyroid tumors." (PMID 30760304, 2019). "On the other hand, Tshr, Pax8 and Nkx2-1 mRNA expressions remained unaltered in thyroid tumors compared to WT thyroids in 2- and 8-month-old mice." (PMID 41002430, 2025). "Markers such as Tg, TTF-1, and PAX8 typically indicate primary thyroid tumors since SITs lack these markers." (PMID 39980562, 2025). "PAX8 positivity is demonstrated in many cases of thyroid tumors in which it acts by regulating the proliferation rate of neoplastic cells." (PMID 40506992, 2025). "The highest rate of PAX8 positivity was found in thyroidal neoplasms of follicular origin (98.6–100%), gynecological carcinomas (up to 100%), renal tumors (82.6–97.8%), and urothelial neoplasms (2.3–23.7%)." (PMID 39105782, 2024). "The highest rate of PAX8 positivity was found in thyroidal neoplasms of follicular origin (98.6–100%), gynecological adenocarcinomas (up to 100%), renal tumors (82.6–97.8%), and urothelial neoplasms (2.3–23.7%)." (PMID 39105782, 2024). "Our study demonstrates that thyroid tumour cells expressing Pax8 after stable transfection become able to uptake the radioiodine, even if in absence of a full recovery of NIS protein expression on their plasmamembrane." (PMID 16029487, 2005). "In accordance with this pattern of developmental expression, in addition to RCCs, PAX8 consistently stains Műllerian neoplasms and thyroid neoplasms, and, in smaller subsets (~20%), urothelial carcinomas of the renal pelvis, Wolffian duct lesions, and thymic neoplasms." (PMID 36428491, 2022). "It has been reported that a progressive decrease of PAX8 levels occurs in thyroid tumors from follicular adenoma to differentiated carcinoma and then to anaplastic carcinoma, which parallels the progressive dedifferentiation and increasing malignancy of thyroid tumors." (PMID 26030152, 2015). "In addition to hypothyroidism, PAX8 has a role in a subset of renal, bladder, ovarian, pancreatic endocrine and thyroid neoplasm." (PMID 26030152, 2015). "Indeed, several studies reported a reduced TiTF1, PAX8 or FOXE1 expression in human thyroid tumors, especially in the poorly differentiated carcinomas." (PMID 22242190, 2012). "Our data, therefore, represent a very promising starting point for further investigations and strategies exploiting this effect of Pax8, eventually in combination of other thyroid-specific transcription factors, for extending radioiodine treatment also to the less differentiated thyroid tumours." (PMID 16029487, 2005). "Moreover, reduction/lost of Pax8 expression has been described in thyroid tumour tissues and cell lines [, our unpublished observations]." (PMID 16029487, 2005). "Notably, double-negative PAX8/SOX17 status completely excluded Müllerian origin in metastases from colorectal, breast, and pulmonary primary tumors (100% specificity), though renal (all PAX8+) and thyroid neoplasms (63.6% PAX8+) required additional markers for distinction." (PMID 41664069, 2026). "Our previous findings about mRNA levels of thyroid specific transcription factors in thyroid tumours corroborate this hypothesis: both PAX8 and FOXE1 follow a similar expression pattern than DREAM, being highly expressed in benignant lesions compared to malignant lesions." (PMID 29641740, 2018). "Therefore, it is expected that the expression pattern of PAX8/PPARγ fusion protein is associated with the differentiation behaviour of thyroid tumours, where absent or low level is expected in poorly differentiated tumours and high level in well-differentiated tumours." (PMID 39558949, 2024). "In contrast, PAX8, TTF1, and CDX2, markers for renal carcinomas, pulmonary and thyroid neoplasms, and small intestine or the appendix, respectively, were constantly negative in all RenNETs of our series and in the cases of the literature." (PMID 37405461, 2023).
thyroid tumor (continued). "We found that PAX8 and NKX2-1 levels are significantly reduced in DICER1-silenced human thyroid tumor cells, whereas the opposite is seen in DICER1 overexpressing cells." (PMID 33176626, 2021). "Moreover, it has been extensively demonstrated that a progressive decrease of Pax8 level occurs in thyroid tumors from follicular adenoma to differentiated carcinoma and then to anaplastic carcinoma, which parallels the progressive dedifferentiation and increasing malignancy of thyroid tumors." (PMID 25270402, 2014). "It is a widely used cell line which resembles the behaviour of poorly differentiated thyroid tumours, including a very low iodide uptake function as well as lost of NIS and Pax8 gene expression, together with several other markers of thyrocyte differentiation." (PMID 16029487, 2005). "In this case, we did not check PAX-8 expression because we thought that it will not contribute to the diagnosis since PAX-8 expression can be detected in different tumors other than thyroid tumor, such as renal cancer." (PMID 32748087, 2020). "In summary, we have demonstrated underexpression of PPARγ in PAX8/PPARγ-negative thyroid tumours of follicular origin, and that a further reduction of PPARγ expression is associated with dedifferentiation at later stages of tumour development." (PMID 15238980, 2004). "Furthermore, PAX8-PPARγ expression was found to correlate with key clinical parameters, including tumor differentiation, TNM stage, and lymph node metastasis, indicating a potential role in thyroid tumor development and progression." (PMID 40506992, 2025). "PAX2 stains similarly to PAX8; with the possibly useful difference of negative PAX2 staining in thyroid neoplasms, admittedly only reported in small series." (PMID 36428491, 2022). "Although the immunophenotype of our case indicated epithelioid–squamoid differentiation, the characteristic expression patterns of TTF-1, Pax-8, and CD5 were absent in the thyroid tumor." (PMID 29885658, 2018). "We and others have detected cases of thyroid tumours, such as FTC, FTA or PTC, that exhibit mild or moderate diffuse PPARγ nuclear staining, even though they are RT–PCR negative for the PAX8-PPARγ fusion gene." (PMID 15238980, 2004).
papillary thyroid carcinoma (28 papers, 2004 to 2025). "Gene fusions were almost exclusively (28 of 29 [97%]) found in papillary carcinomas, with 1 poorly differentiated carcinoma harboring a PAX8-PPARG fusion." (PMID 35679040, 2022). "MiR-144-3p also proved to be an EMT inducer in papillary thyroid cancer, as it was responsible for decreased E-cadherin and thyroid-specific transcription factor PAX8 expression while upregulating vimentin and N-cadherin." (PMID 34680488, 2021). "HE staining of bone metastases revealed nuclear features of papillary carcinoma, and immunostaining was positive for thyroglobulin and PAX-8." (PMID 32328315, 2020). "The 6 papillary CNS metastases had a complete prior workup with IHCs confirming their origin, such as TTF1 and thyroglobulin for papillary thyroid carcinoma, TTF1, CK7, CK20 for lung adenocarcinoma, and Pax8, WT1, CK7, CK20 for serous carcinoma of the ovary." (PMID 27229317, 2016). "TL-LGNPPA was negative for TG and PAX-8, whereas papillary thyroid carcinoma was positive for TG and PAX-8." (PMID 36705380, 2023). "After isolation, CD133+ cells exhibited higher radioresistance and higher expression of Oct4, Nanog, Sox2, Lin28 and Glut1 in the cell line or primarily cultured papillary thyroid cancer cells, and lower expression of various thyroid-specific genes, namely NIS, Tg, TPO, TSHR, TTF1 and Pax8." (PMID 23081821, 2013). "Moreover, treatment of TPC-1 and BCPAP cells for 24 h with trametinib, a MEK inhibitor which was shown to reduce HMGA2 mRNA expression levels, increased TG, TPO and PAX8 mRNA levels, suggesting that the MAPK pathway induces cell dedifferentiation in papillary thyroid carcinomas through HMGA2." (PMID 40004107, 2025). "Recently, we have demonstrated that TAZ acts as a potent regulator of Pax8 and TTF-1 activity and we have also reported that TAZ, already known to promote cell proliferation and to induce epithelial–mesenchymal transition, is overexpressed in papillary thyroid cancer." (PMID 21966443, 2011).
serous ovarian cancer (27 papers, 2015 to 2026). "PAX8 has most frequently been associated with the development of high-grade serous ovarian cancers (HGSOCs); but as this and other studies have shown, PAX8 is commonly expressed by other major EOC histotypes." (PMID 29312534, 2017). "Pax8 is expressed in almost 90% of high-grade serous ovarian cancer and is a commonly used marker to classify ovarian serous tumors." (PMID 38791431, 2024). "PAX8 is a lineage‐specific transcription factor involved in the epithelial development of the fallopian tube and express in high‐grade serous ovarian carcinoma derived from both the fallopian tube and ovarian surface epithelium." (PMID 33830648, 2021). "The murine OSE (MOSE) does not endogenously express PAX8, yet there are several OSE-derived serous ovarian cancer models that acquire PAX8 expression." (PMID 27129161, 2016). "Paired box protein Pax-8 (PAX8) is a critical lineage marker and master regulator of transcription in high-grade serous ovarian carcinoma (HGSC)-the most common subtype of epithelial ovarian cancer-driving cell proliferation and migration and resisting apoptosis." (PMID 42011738, 2026). "Moreover, in high-grade serous ovarian cancer, PAX8 is targeted by micelle-encapsulated TST, resulting in limited tumour growth." (PMID 35859150, 2022). "Moreover, tumor cells were stained by PAX8, suggesting human high-grade serous ovarian carcinoma." (PMID 35864492, 2022). "In addition, by binning TCGA high-grade serous ovarian cancer (HGSOC) cases (n = 430) based on either PAX8 or PRDM3 expression quartiles, we observed that cases with high PAX8 and MECOM expression displayed significantly higher Signature Score compared to others." (PMID 33903593, 2021). "For example, in high-grade serous ovarian cancer (HGSOC), ALDH1+ or CD133+ CSCs regenerate glandular (EpCAM+/PAX8+) and invasive subpopulations, reconstructing the original tumor’s heterogeneity." (PMID 41009433, 2025). "High PAX8 expression was associated with low tumor grade in 365 non-invasive papillary urothelial carcinomas (p < 0.0001) but unrelated to patient outcome and/or tumor phenotype in clear cell renal cell carcinoma, high-grade serous ovarian cancer, and endometrioid endometrial carcinoma." (PMID 39105782, 2024). "PAX8 is overexpressed in about 80% of the most common EOC histotype, high-grade serous ovarian cancer (HGSOC)." (PMID 29312534, 2017). "The transcription factors MECOM, PAX8, SOX17 and WT1 are candidate master regulators of high-grade serous 'ovarian' cancer (HGSC), yet their cooperative role in the hypothesized tissue of origin, the fallopian tube secretory epithelium (FTSEC) is unknown." (PMID 37090516, 2023). "The presented efficacy and safety data of the bivalent low affinity anti-LYPD1 TCB QZC131 directed against the PAX8 lineage-driven target LYPD1 supports its therapeutic potential and merits further evaluation as a treatment for advanced high-grade serous ovarian cancer." (PMID 34290299, 2021). "Neither PAX8 nor PAX8-responsive regulon predicted high-grade serous ovarian cancer patient prognosis using the median expression cutoff." (PMID 31050342, 2019). "There was significant variation in PAX8 expression across EOC histotypes (p < 0.0002, one-way ANOVA), with PAX8 overexpressed in serous ovarian cancer (n=16), CCOC (n=18) and MOC cell lines (n=2), but not in EnOC lines (n=3) lines." (PMID 29312534, 2017). "WT1, CA 125, and PAX8 are usually positive in high-grade serous ovarian carcinoma and negative in breast carcinoma; however, in some cases of breast cancer, CA 125 and WT1 also might be positive." (PMID 28730323, 2017).
serous ovarian cancer (continued). "As expected, the initial tumor and all the models harbored nuclear expression of PAX8, a marker for carcinoma of Müllerian origin, and no expression of WT1, a robust prognostic marker selectively expressed in some high-grade serous ovarian carcinoma." (PMID 37803448, 2023).
serous carcinoma (26 papers, 2013 to 2026). "Found STIC exclusively in serous carcinoma cases and indicated PAX8 expression as significantly associated with serous tumors." (PMID 39040787, 2024). "Moreover, PAX8 has a diagnostic value as Müllerian differentiation marker in peritoneal effusions demonstrating the origin in high- and low-grade serous carcinomas." (PMID 23958394, 2013). "In a previous study, immunohistochemistry was carried out using PAX8 on 102 low-grade serous neoplasms of the ovary, including both SBTs and well-differentiated serous carcinoma, and PAX8 staining was seen in 100% samples." (PMID 35326657, 2022). "In contrast, the mean PAX8 expression levels were similar in serous borderline tumors (9.978) and serous carcinomas (9.989; p = 7.03 × 10−1)." (PMID 36552773, 2022). "The same study also reported that PAX8 is negatively expressed in serous carcinoma but is positively expressed in breast carcinomas." (PMID 34917619, 2021). "We aimed to determine the effects of PAX8 expression on the migrative, adhesive and survival capabilities of high-grade serous carcinoma cells." (PMID 31832016, 2019). "Serous adenocarcinomas with positive PAX-8 staining can occur at primary sites including the ovary and uterine corpus and cervix, making it difficult to identify the anatomical origin in women with genital tract PAX-8-positive serous adenocarcinomas." (PMID 29433539, 2018). "However, multiple lines of evidence from previous studies have rendered support to a tubal origin of these lesions (e.g., based on Pax8 or Ovgp1-based genetic targeting), in particular the serous adenocarcinoma." (PMID 35159108, 2022). "Serial passaging of the normal OSE transforms cells into serous carcinoma with PAX8 expressed." (PMID 30096791, 2018). "BAP1 is retained in almost all serous carcinomas, making it useful to differentiate between malignant mesothelioma and serous carcinoma, additional panel could include paired box 8 (PAX8) (usually positive in serous carcinoma) and calretinin (usually positive in mesothelial cells)." (PMID 36069384, 2022). "Thus, this GATA3-MGP-TRPS1 panel may need inclusion with Pax-8 and WT-1 to differentiate breast carcinoma from serous carcinoma." (PMID 36284362, 2022). "Overall, PAX8 could be a potential therapeutic target for high-grade serous carcinoma." (PMID 31832016, 2019). "Disrupting these interactions may mediate the deleterious effects of PAX8 in serous carcinoma." (PMID 30096791, 2018). "Pitfalls exist: PAX8 (MRQ50 clone) and WT1 may be positive in high-grade serous carcinomas but can occasionally stain TNBC, necessitating careful interpretation." (PMID 41301002, 2025).
serous carcinoma (continued). "Moreover, the tumors exhibited diffuse expression of PAX8, WT1, and CK7, but no CK20 expression, suggesting that they were high-grade serous carcinomas with Müllerian origin." (PMID 29560094, 2018).